AR (androgen receptor)
Diseases named in the same sentence as AR in open-access papers (continued):
Sharing a sentence is not in itself a finding about the gene and the disease.
prostate carcinoma (continued). "PC-3 cells are non-hormonal dependent human prostate cancer cells, lacking androgen receptor and prostate-specific antigen, resulting in a poor treatment effect with hormone therapy in the later stage." (PMID 34563040, 2021). "For example, in breast and prostate cancer SFPQ appears to be an important driver of the cancer phenotype via post-transcriptional regulation of key genes such as oestrogen receptor α (ERα) and androgen receptor (AR), respectively." (PMID 34218270, 2021). "Since PCAL7 was highly expressed in AR‐dependent prostate cancer cells, we then inspected whether the promoter region of PCAL7 can be occupied by AR." (PMID 33219721, 2021). "By regulating AR functions, RNF6 promotes prostate cancer growth." (PMID 34081837, 2021). "Studies also revealed that overexpressed ERG co-opts prostate-specific master regulatory transcription factors, including AR, HOXB13 and FOXA1, in a process facilitated by their physical interaction with ERG and actives NOTCH signaling in primary prostate cancer." (PMID 34630112, 2021). "Given taxanes represent first- and second-line chemotherapy for PCa it was significant that docetaxel inhibited prostate cancer cell xenografts expressing AR-v567, but not xenografts with AR-v7." (PMID 33572755, 2021). "It has been reported that CAMK2N1 expression is downregulated after androgen receptor (AR) activation in human prostate cancer cell lines following an auto-regulatory negative feedback loop." (PMID 33441551, 2021). "For example, when AR drives expression of ERG from the common TMPRSS2:ERG fusion, both of these factors have been recently described to be involved in the regulation of long non-coding RNAs (lncRNAs) in prostate cancer." (PMID 33634124, 2021). "Androgen receptor may also attach with LEF transcription factor, influencing β-catenin and prostate cancer progression." (PMID 35201496, 2021). "By physically interacting with AR NTD, BRD4 plays a critical role in facilitating AR-mediated transcription; clinical evaluation of BET inhibitors is currently underway in castration-resistant prostate cancer (clinical trial: NCT03035591)." (PMID 34417184, 2021). "While TMPRSS2-ERG activates NO-cGMP signaling in prostate cancer cells, sGC inhibitor treatment repressed tumor growth in TMPRSS2-ERG-positive VCaP xenograft models and acted in synergy with enzalutamide, the potent AR antagonist." (PMID 33634124, 2021). "However, in breast and prostate cancer, EGF induces the formation of a complex between the EGFR, androgen receptor (AR), estrogen receptor (ER) and Src kinase." (PMID 34067095, 2021). "In turn, androgen receptor and androgen synthesis represent pivotal therapeutic targets (androgen deprivation therapy or ADT), and a variety of anticancer agents targeting this hormonal program has proven to hamper prostate cancer progression." (PMID 34503116, 2021). "This study provides the first evidence on PAM-induced cell cycle arrest in prostate cancer cells, and shed novel insights on therapeutic strategies against AR-negative prostate cancers through cell cycle blockage." (PMID 34476012, 2021). "The AKT3 targeting strategy is specifically effective for ER-negative, androgen receptor (AR)-negative breast or prostate cancer cells." (PMID 33861751, 2021). "Prostate cancer cells are also able to convert weaker androgens produced by the adrenal glands, such as androstenedione and dehydroepiandrosterone (DHEA), into testosterone and DHT, which have a higher affinity for AR." (PMID 33672595, 2021). "Moreover, PCAT1 was identified as an androgen late-response gene and interacted with AR and lysine-specific demethylase 1 (LSD1) upon prolonged androgen treatment to promote prostate cancer growth." (PMID 34946977, 2021). "In prostate cancer, MARCH6 expression was positively correlated with androgen receptor expression." (PMID 34512155, 2021). "They accelerate cell proliferation in AR-positive or AR-negative prostate cancer cells, respectively." (PMID 34356101, 2021).
prostate carcinoma (continued). "Overexpression of WDR62 significantly increased clonogenic survival of both malignant and benign prostate cells suggesting WDR62 is a driver gene in prostate cancer that is likely independent of AR." (PMID 34326322, 2021). "Collectively, our results suggest PRPF6 is involved in enhancement of oncogenic AR signaling, which support a previously unknown role of PRPF6 during progression of prostate cancer and castration-resistant prostate cancers." (PMID 33390843, 2021). "MRV infection can reduce the activity of activated Akt and AR proteins and the expression of PSA in prostate cancer cells, so it may inhibit the progression of prostate cancer to CRPC." (PMID 34956913, 2021). "The results of the study thus imply that inhibition of AR function leads to increased neuroendocrine phenotype and novel experimental strategies should be discussed in order to improve prostate cancer treatment." (PMID 34204596, 2021). "However, PCa eventually progresses to castration‐resistant prostate cancer (CRPC), largely because of androgen receptor variation and increased intratumoral androgen synthesis." (PMID 34185414, 2021). "AR-Vs have been detected in normal prostate and treatment-naive prostate cancer, however, they are much more common in CRPC, leading to the hypothesis that AR-Vs are created in higher quantities due to treatment pressure." (PMID 33993099, 2021). "A literature review focusing on AR, GATA3 and ZNF622 regulation of glycogenes identified a single paper reporting AR binding to a B3GNT5 promoter, using semi-quantitative PCR with ChIP in prostate cancer cell line LAPC-4." (PMID 34283051, 2021). "The p38 MAPK inhibitor decreased cell proliferation under both normoxia and hypoxia in AR positive prostate cancer cells (VCaP, LNCaP, V16D), but not in AR-null prostate cancer cells (DU145, PC3)." (PMID 33671134, 2021). "SHOT-RNA, which is not induced by stress, is particularly highly expressed in androgen receptor (AR)-positive prostate cancer cells and estrogen receptor (ER)-positive breast cancer and is not expressed in other cancers at present." (PMID 33391486, 2021). "In addition to AR, TMPRSS2‐ERG rearrangements, resulting from fusion of an ERG oncogene and AR‐driven TMPRSS2 promoter, have been detected in more than 50% of prostate cancer patients." (PMID 33448107, 2021). "DU145 cells are androgen-independent prostate cancer cells with low levels of differentiation and lack of endogenous AR expression." (PMID 34073059, 2021). "The other major difference between the previously reported results in the DU145 AR negative prostate cancer cell line suggests bergamottin’s action is CYP3A5—AR signaling dependent." (PMID 34570813, 2021). "Previous studies revealed that niclosamide suppressed AR negative prostate cancer cell growth; here we showed that both ARVib-7 and ARVib-31 suppressed DU145 and PC3 cells in a dose-dependent manner." (PMID 34272475, 2021). "It has been noted that Wnt3a can impact the progression of prostate cancer by enhancing the expression of cytosolic and nuclear β-catenin in addition to enhancing androgen receptor activity or inducing activity in absence of the androgen hormone." (PMID 35201496, 2021). "Despite absence of metastatic disease, patients with nonmetastatic castrate-resistant prostate cancer receiving newer androgen receptor inhibitors can experience decreased bone mineral density." (PMID 33028943, 2021). "AR activity sustains CAMKK2 expression and this supports prostate cancer cell proliferation." (PMID 34725334, 2021). "In addition, in prostate cancer, PCGEM1 inhibits HnRNPA1-mediated AS in androgen receptor pre-mRNA, promoting castration resistance (including drug resistance to enzalutamide and abiraterone)." (PMID 33407694, 2021). "The percentage of AR double-negative tumors has risen from 5% to more than 20% in the last 10 years, making it the most frequent subtype of AR negative prostate cancers." (PMID 33420371, 2021).
prostate carcinoma (continued). "So far it has not been tested for its ability to block AR activation which is very relevant in prostate cancer." (PMID 34570813, 2021). "Although these models do not directly result in novel prostate cancer treatments, their impact is indirect by improving the understanding of the AR and its pathways." (PMID 33671614, 2021). "Advanced prostate cancer is treated with radical prostatectomy, radiotherapy, chemotherapy, and androgen-deprivation therapy (ADT) through physical or chemical castration to repress androgen-induced AR signaling." (PMID 33535458, 2021). "Although PC3 and PC3CR cells are neuroendocrine marker negative and AR signaling negative prostate cancer, VP16 was considered effective for some types of refractory prostate cancer." (PMID 34782700, 2021). "Moreover, in prostate cancer, SLC35F2 seems to play a role, as it was highly expressed, directly upregulated by the androgen receptor (AR) activation and crucially involved in the sensitivity of prostate cancer cells to YM155." (PMID 33418944, 2021). "Inhibition of multiple pathways, including those of AR and STAT-3 in prostate cancer, could be achieved by treatment with galiellalactone." (PMID 34204596, 2021). "In the absence of androgen receptor (AR) signaling, the glucocorticoid receptor (GR) is a major contributor to disease progression and drug resistance in prostate cancer." (PMID 34680291, 2021). "Although the authors did not explain the mechanism of NGF-mediated AR re-expression in prostate cancer cells, NGF administration can downregulate DNA methyltransferases in other cells." (PMID 33420371, 2021). "In fact, the regulation of AR expression and function by USP22 in prostate cancer has been reported, but whether AR-V7 could be regulated by USP22 is elusive." (PMID 34548474, 2021). "Importantly, new model systems that easily switch from AR-positive to AR-negative could be developed and subsequently used to identify additional key molecular features associated with the switch from AR-positive to -negative prostate cancer." (PMID 33420371, 2021). "Since it is known that the SRC kinase promotes AR transactivation function this could be the mechanism through which upstream HH-GLI signaling sustains AR signaling and contributes to prostate cancer cell growth." (PMID 34290270, 2021). "Melatonin inhibits the proliferation of prostate cancer cells through MT1 receptor-mediated mechanisms including activation of protein kinase A and protein kinase C, inhibition of the NF-κB activation and modulation of androgen receptor signaling." (PMID 35008896, 2021). "In addition, ARV-110 specifically degrades AR ≥ 95% in ENZ-treated and drug-resistant prostate cancer xenograft models." (PMID 34488823, 2021). "That said, it remains largely unclear how generalizable these findings are and if AR re-activation will suppress the oncogenic potential of AR-negative prostate cancer or in some cases rather boost tumor growth." (PMID 33420371, 2021). "Our findings suggest that co-inhibition of AR and BRAF in BRAF-mutant prostate cancer patients could be particularly effective." (PMID 34211036, 2021). "The researchers used two prostate cancer cell lines, LNCaP and CWR22Rv1 cells, to prove that metformin does not affect the degradation or stability of AR protein; however, it suppresses the AR signaling pathway by repressing AR mRNA expression." (PMID 34053455, 2021). "In prostate cancer, as a key upstream regulator of TRIM24, TRIM28 was proved to interact with TRIM24 to prevent its ubiquitination and degradation by SPOP and also enhance the signal transduction of Androgen receptor (AR)." (PMID 33817325, 2021). "It was known that AR amplification sensitizes prostate cancers to low levels of androgen, that PI3K (PIK3CA/B) and Wnt (RSPO2) pathways can bypass the AR function for cell proliferation, and that CCND1 regulates the cell cycle; therefore, all five genes are involved in mCRPC." (PMID 34439974, 2021).
prostate carcinoma (continued). "We demonstrated both in vitro and in vivo that WDR62 promotes aggressive prostate cancer phenotypes in all of the prostate cancer models that were tested, irrespective of AR-status, suggesting that this is an AR-independent human prostate cancer driver gene." (PMID 34326322, 2021). "A recent study showed that radiation treatment enhances the expression of both LGR4 and its ligands in AR-positive and negative prostate cancer cells." (PMID 33946652, 2021). "Urolithin A's chemopreventive effects have been tested on androgen receptor-negative prostate cancer cell lines such as PC-3 and androgen receptor-positive prostate cancer cell lines such as C4-2B." (PMID 34164422, 2021). "Additionally, the blockade of AR signaling increases the PI3K activation cascade, enabling prostate cancer cell survival." (PMID 34948314, 2021). "In prostate cancer, EZH2 activates AR gene transcription through direct occupancy at its promoter." (PMID 34776951, 2021). "EPI-001 showed to be non-specific to the AR, however, where it inhibited the growth of AR-negative prostate cancer cell lines as well as in a breast carcinoma cell line where it modulated both oestrogen and progesterone receptors." (PMID 33993099, 2021). "By targeting both AR and the TME, RSV can induce growth inhibition, cell cycle arrest, apoptosis, as well as inhibit metastasis of different cancer types, including prostate cancer." (PMID 33535458, 2021). "In prostate cancer, the loss of MALAT1 impedes the growth of PCa xenografts and reduces cell proliferation and migration, while it promotes apoptosis in AR-negative prostate cancer cells." (PMID 33672595, 2021). "In parallel to ER-targeted PET imaging in breast cancer with 16α-18F-fluoro-17β-estradiol ([18F]FES), androgen receptor (AR)-targeted PET imaging in prostate cancer is possible using 18F-fluorodihydrotestosterone (18F-FDHT), which binds the intracellular AR in prostate cancer cells." (PMID 34869009, 2021). "Although the androgen receptor (AR) is not the only driver of prostate carcinogenesis, almost 80–90% of prostate cancers are dependent on androgenic activity via AR signaling." (PMID 34386489, 2021). "It is firmly established that suppression of AR transcriptional activity through reduction in circulating androgens or direct antagonism of AR-androgen binding using AR competitive antagonists reduces expression and protein levels of TMPRSS2 within the prostate, as well as within prostate cancers." (PMID 34225789, 2021). "A similar AR activity is also observed in prostate cancer where AR fails to activate NKX3.1 but promotes the expression of PSA and FKBP51 among others." (PMID 33884281, 2021). "While it is known that AR promotes gene fusion formation in prostate cancer, an androgen-dependent mechanism for EWSR1 breakage has not been shown." (PMID 34409300, 2021). "Androgen receptor (AR)- and low-density lipoprotein receptor-related protein-1 (LRP1)-positive prostate cancer cell line, LNCaP is more sensitive to emodin than AR-negative LRP-positive prostate cancer cells, PC-3 cells." (PMID 34073059, 2021). "Strictly speaking, this mechanism of prostate cancers is not androgen-independent and the responses still depend on AR and androgen." (PMID 34630112, 2021). "Additional markers for primary prostatic cancers have been investigated, including prostate-specific membrane antigen (PSMA), prostate-specific acid phosphatase (PSAP), prostein (also known as p501s or SLC45A3), ETS-related gene (ERG), androgen receptor (AR)." (PMID 33450939, 2021). "Similarly, in PTEN-negative prostate cancer, PI3K/AKT signaling is activated and the downregulation of FOXO1 contributes to the hyperactivation of AR, thereby driving the castration-resistant progression of PC." (PMID 33921222, 2021). "The levels of Pin1 protein were detected in all five of the human prostate cancer cell lines examined and were highest in androgen-sensitive LNCaP cells and lower in AR-negative PC-3 and DU145 cells." (PMID 33753863, 2021).
prostate carcinoma (continued). "The SAM pointed domain-containing ETS transcription factor (E26 transcription factor) is expressed in prostate cancer that is regulated by AR signaling and has a negative correlation with CCL2." (PMID 34445235, 2021). "These functional experiments found that AC016745.3 and NONO still play a role in AR-negative prostate cancer cells." (PMID 34833084, 2021). "Employing 5-Aza treatment could trigger demethylation of AR promoter and as a consequence the expression level of IGF1R could increase significantly which may consider as a promising therapy in human prostate cancer." (PMID 33768092, 2021). "Collectively, these data demonstrate that KLF5 overexpression regulates ERBB2 expression in AR-positive prostate cancer cells and more broadly regulates ERBB2-related genes LGALS7 and FAM129B in prostate cancer cells regardless of cellular AR status." (PMID 34737261, 2021). "In the cytoplasm, ligand‐bound AR interacts with protein kinases such as SRC and PI3K via its N terminus to initiate signal transduction pathways that modulate cellular proliferation and migration in prostate cancer cell lines." (PMID 33797847, 2021). "Elucidation of the crystal structures of the AR DNA binding domain (DBD) and the LBD provides a new framework for understanding the functions of this receptor and has led to the development of rational drug design for the treatment of prostate cancer." (PMID 33672769, 2021). "Therefore, AR, PGC1A and HSPB1 (HSP27) down-regulation by phages exposures can be explored as potential strategies for prostate cancer therapies." (PMID 34578333, 2021). "In prostate cancers, castration-resistant prostate cancer (CRPC) occurs within a few years of androgen-deprivation therapy (ADT), and a key driver of the malignant progression is the androgen receptor (AR)." (PMID 34439974, 2021). "In prostate cancer cells, β‐catenin was shown to selectively bind to AR in an androgen (but not estrogen) dependent manner." (PMID 33085215, 2021). "This shows that the intracellular Wnt/β-catenin signaling is interactive and can impact prostate cancer progression with and without the aid of other genes like androgen receptor and MMP-7." (PMID 35201496, 2021). "Since androgen receptor (AR) signaling is the main pathway ensuring prostate cancer cell growth, androgen deprivation therapy (ADT) has been the standard treatment option for patients with advanced forms of prostate cancer." (PMID 34290270, 2021). "Also, AR has been demonstrated to directly bind to the regulatory regions of both IRE1α and XBP-1 and regulate their expression in prostate cancer cells." (PMID 34295814, 2021). "Dihydrotestosterone (DHT, AR activator) induces the expression of ACE2 and TMPRSS2 in activin-sensitive prostate cancer cells (LNCaP) and A549 non-small cell lung cancer cells, and GT0918 (a new generation of AR antagonists) can inhibit DHT-induced expression of ACE2 and TMPRSS2." (PMID 33396184, 2020). "There was an obvious decrease in β-catenin, p-AKT, and p-mTOR in cir-ITCH-overexpressed prostate cancer cells, and in both androgen receptor-positive LNCaP cells and androgen receptor-negative PC-3 cells." (PMID 32904490, 2020). "On the one hand, ARGs that are included in the analysis to generate the AR-Scores and subsequently to infer the AR activity have previously been validated in prostate cancer, but not in HCC cell lines." (PMID 33328560, 2020). "PCSCs were isolated from the non-adherent 3D-cultured prostatospheroids derived from three different prostate cancer cell lines (AR-positive, LNCaP and VCaP; AR-negative, DU145)." (PMID 32183880, 2020). "It is possible that, unlike prostate cancer, despite AR expression, the AR signalling pathway is not the most critical driver of tumour progression in recurrent EOC, and inhibition of this pathway alone is therefore insufficient to cause significant response." (PMID 33854564, 2020).